SPANXA1 (sperm protein associated with the nucleus, X-linked, family member A1)
Synonyms: CT11.1; SPAN-X; SPANX-A; NAP-X; SPAN-Xa; SPAN-Xb; CT11.3; SPANX
Tractability: No criterion of Open Targets' tractability assessment is met for any kind of drug.
Gene: Protein-coding gene on chromosome X (141,583,674 to 141,584,738, reverse strand). Ensembl gene ENSG00000198021.
Subcellular location: Cytoplasm; Nucleus
Subcellular location (Human Protein Atlas): Nucleoplasm; Vesicles
Gene Ontology:
Molecular function: protein binding
Biological process: spermatogenesis
Cellular component: nucleus; cytoplasm
Homologues: Paralogues in human: SPANXA2 (100% identical), SPANXC (94% identical), SPANXD (94% identical), SPANXB1 (85% identical).
Diseases named in the same sentence as SPANXA1 in open-access papers:
SPANXA1 is named in the same sentence as 2 diseases in open-access papers, as found by Europe PMC text mining. Sharing a sentence is not in itself a finding about the gene and the disease. The quoted sentences say what the papers report.
melanoma (1 paper, 2020). A malignant, usually aggressive tumor composed of atypical, neoplastic melanocytes. "Meanwhile, profiles of expression of HAGE, PASD1, SEMG1, SLLP1, SPANXA1, SSX1 weren’t significantly different in STBS and melanoma cell cultures at the complex assessment." (PMID 32042403, 2020).
cancer (1 paper, 2016). A tumor composed of atypical neoplastic, often pleomorphic cells that invade other tissues. "SPANXA1 a member of the SPANX-A/D cluster of SPANX gene located on Xq27 has been found highly expressed in cancer as well." (PMID 26885621, 2016).